PPARG (peroxisome proliferator activated receptor gamma)
Diseases named in the same sentence as PPARG in open-access papers (continued):
Sharing a sentence is not in itself a finding about the gene and the disease.
Autoimmunity (12 papers, 2014 to 2024). The occurrence of an immune reaction against the organism's own cells or tissues. "The role of T-cell PPARγ in lymphopenia-associated autoimmunity was determined for the first time." (PMID 39062500, 2024). "Additionally, ω-3 PUFAs are known ligands for PPARγ, a transcription factor that can hamper NF-kB-dependent transcription of genes associated with inflammation and autoimmunity." (PMID 33897700, 2021). "PPARs, particularly PPARγ, have been linked to both T‐cell function and autoimmunity." (PMID 32246891, 2020). "PPARγ has specifically been shown to be a negative regulator of T cell activation, regulating interleukin-2 (IL-2) production in activated T cells, and the loss of PPARγ in T cells contributes to autoimmunity." (PMID 27929420, 2016). "Thus, PPARγ loss implicates the susceptibility of an individual to autoimmunity." (PMID 27221351, 2016). "PPARγ has been recently studied in T cells where it was shown to regulate Th17 cells to prevent autoimmunity and was also found to be necessary for regulatory T cell functions." (PMID 27335315, 2016). "Here, for the first time, we characterized CD4-PPARγKO mice to investigate the intrinsic role of PPARγ in T cells and autoimmunity related to TFH cells and GC reaction." (PMID 24921943, 2014). "Finally, this study endorses the essential role of PPARγ in driving autoimmunity and disease progression in MS." (PMID 37041314, 2023). "Whether PPARγ pathway is also involved in Th17-mediated autoimmunity in SS and whether PPARγ activation contributes to the attenuation of Th17 response by ADF in this disease-setting require future delineations." (PMID 36430269, 2022). "Nuclear receptors, such as the glucocorticoid receptor (GR), the retinoid x receptors (RXR), the peroxisomal proliferator‐activated receptor α (PPARα), and gamma (PPARγ), are targets of already approved drugs for the treatment of autoimmunity, cancer, hyperlipidemia, or type 2 diabetes." (PMID 32246891, 2020). "PPARγ is an important regulator of effector T cell functions, as PPARγ-deficient CD4+ T cells cannot proliferate and survive in a lymphopenic environment and hence are less capable of inducing autoimmunity and graft-versus-host disease in mice." (PMID 28337199, 2017). "Because the disturbance and hyperactivation of the immune system are frequently associated with splenomegaly, we hypothesized that immunological homeostasis is disrupted at a certain low level of PPARγ expression, consequently enhancing humoral responses and resulting in autoimmunity." (PMID 27221351, 2016). "We demonstrate that PPARγ plays a significant role in the regulation of TFH responses, especially in females, which would be important to prevent autoimmunity." (PMID 27335315, 2016). "Although previous studies focused on PPARγ agonists revealed its regulatory function in T cells, the mechanism and intrinsic roles of this nuclear receptor in TFH cells and autoimmunity is largely uncharacterized." (PMID 24921943, 2014). "In conclusion, we have revealed the importance of PPARγ in regulating T cell activation related to TFH cells and autoimmunity." (PMID 24921943, 2014). "Collectively, these results suggest that PPARγ has a regulatory role for TFH cells and germinal center reaction to prevent autoimmunity." (PMID 24921943, 2014). "A novel tool for revealing the actual functions of PPARγ in the development of autoimmunity without stimulating specific antigens is required." (PMID 27221351, 2016).
chronic obstructive pulmonary disease (12 papers, 2005 to 2025). A chronic and progressive lung disorder characterized by the loss of elasticity of the bronchial tree and the air sacs, destruction of the air sacs wall, thickening of the bronchial wall, and mucous accumulation in the bronchial tree. "Previous study indicated that PPARγ activation attenuates lipopolysaccharide-induced inflammation in mouse models, suggesting potential benefits in inflammatory diseases such as chronic obstructive pulmonary disease (COPD)." (PMID 41357323, 2025). "In addition, PPARγ plays a protective role in ALI, lung cancer, chronic obstructive pulmonary disease, and other respiratory diseases." (PMID 36213491, 2022). "A comparison ofnonsmokers, smokers with chronic obstructive pulmonary disease(COPD), and smokers without COPD found no statisticallysignificant difference in the number of PPARγ-positivemacrophages, but found an increased number ofPPARα-positive alveolar macrophages in smokers with COPD." (PMID 17710235, 2007).
epilepsy (12 papers, 2015 to 2025). A brain disorder characterized by episodes of abnormally increased neuronal discharge resulting in transient episodes of sensory or motor neurological dysfunction, or psychic dysfunction. "Owing to the established association between glutamate and tumour associated epilepsy, there may also exist a novel role for PPARγ agonists." (PMID 26046374, 2015). "Overall, this is the first study to investigate the epilepsy-associated risk for developing T2DM and evaluate the effects of AEDs on T2DM-related pathway gene expression and on PPARγ transactivation." (PMID 37334286, 2023). "However, valproic acid has a dose-dependent effect, increasing the expression of PPARγ at therapeutic doses in patients with epilepsy." (PMID 40217882, 2025). "Interestingly, both SGLT2 and PPARγ are known to participate in epileptogenesis, especially PPARγ was considered as a promising therapeutic target of epilepsy." (PMID 29566716, 2018). "Therefore, neuronal ZAG decrease in epilepsy or seizure may be mediated by PPARγ, but whether PPARγ regulates fatty acid β‐oxidation and ketogenesis in neurons via ZAG is unclear." (PMID 32340079, 2020). "Remarkably, the upregulation of PPARγ was found to correlate with the anticonvulsant action of CBD, suggesting a possible contribution of this receptor in epilepsy management." (PMID 40608247, 2025).
Hypoglycemia (12 papers, 2008 to 2025). A decreased concentration of glucose in the blood. "Before the patient was diagnosed with PPARG-DM, he had been taking glimepiride (4 mg/day) and metformin (1,500 mg/day) and had occasional hypoglycemia." (PMID 34764936, 2021). "RLIP76−/− mice have baseline hypoglycemia, and baseline increases in pAMPK, PPARγ, pJNK, and pAKT, which provides perhaps the reason for their hypoglycemia." (PMID 21931813, 2011). "The mechanisms involved were not fully understood, but through the action of their metabolites likely acted on PPARγ, the FRX-CREB axis and their downstream targets to delay the onset of hypoglycemia, inflammation and extend running time." (PMID 33898524, 2021). "Just as PPARγ is constitutively increased in RLIP76−/− mice and may contribute solely or partially to hypoglycemia, it is possible that the observed hypo-triglyceridemia seen in RLIP76−/− mice is due to constitutive activation of PPARγ." (PMID 21931813, 2011). "The activation of PPARγ and the FRX-CREB axis are likely key mechanisms through which SCFAs and bile acids coordinately engage multiple converging pathways to regulate mitochondrial functions, including fatty acid uptake and oxidation to forestall hypoglycemia and ensure longer running time." (PMID 33898524, 2021).
malaria (12 papers, 2010 to 2022). Malaria is a serious and sometimes fatal disease caused by a parasite that commonly infects a certain type of mosquito which feeds on humans. "Peroxisome proliferator-activated receptor-gamma agonists (e.g. rosiglitazone) have been shown to act on several pathways implicated in the pathogenesis of severe malaria and may improve clinical outcome as an adjunctive intervention." (PMID 28535809, 2017). "PPARγ agonists are promising candidates for adjunctive malaria treatment as they have been reported to have anti-inflammatory, anti-oxidant, and neuroprotective properties." (PMID 28535809, 2017). "The use of PPARγ agonists to modulate immune responses to malaria was initially motivated by reports demonstrating that PPARγ regulates CD36 transcription and that PPARγ agonists have anti-inflammatory properties." (PMID 21772838, 2012). "The existing data on the use of PPARγ agonists in malaria are encouraging, with rosiglitazone being safe, well tolerated, and efficacious in uncomplicated malaria patients." (PMID 21772838, 2012). "The conventional way to promote CD36 expression through PPARγ nuclear receptor is inefficient under malaria inflammatory processes." (PMID 21949655, 2011). "During malaria blood stage infection, haemoglobin metabolism by the parasite leads to reactive oxygen species (ROS) production that activates the transcription factors PPARγ and Nrf2." (PMID 26385579, 2015). "Human monocytes and murine macrophages treated with PPARγ agonists generate significantly less TNF in response to malaria-related inflammatory stimuli including parasite lysates and P. falciparum glycosylphosphatidyl inositol (GPI), a malaria toxin that interacts with TLR2." (PMID 21772838, 2012). "Interestingly, PPARγ was one of only two genes in a malaria-resistance locus identified using a genome-wide analysis of inbred mouse lines, supporting a protective role for PPARγ in malaria." (PMID 21772838, 2012). "The current knowledge of PPARγ agonist use in malaria is summarized." (PMID 21772838, 2012). "The current knowledge of PPARγ agonist use in malaria will be summarized." (PMID 21772838, 2012). "However, in inflammatory conditions, we demonstrated that Nrf2 pathway controls CD36 expression and improves the outcome of severe malaria independently of PPARγ." (PMID 21949655, 2011). "Collectively, this report highlights that the Nrf2 transcription factor could be an alternative target to PPARγ in the control of severe malaria through parasite clearance." (PMID 21949655, 2011). "In a murine model of malaria, administration of the PPARγ agonist rosiglitazone, to Plasmodium chabaudi-infected mice, significantly decreased parasitaemia levels in wild type compared to CD36 knock-out mice and improved survival in Plasmodium berghei-ANKA infected groups." (PMID 21411011, 2011). "Finally, it is worth considering whether PPARγ agonists could have an impact on the acquisition of adaptive immunity to malaria via modulatory effects on dendritic cells, T cells, and B cells." (PMID 21772838, 2012). "PPARγ agonists have been proposed as malaria therapeutics and can increase CD36-mediated phagocytosis of iRBCs while reducing malaria-induced TNFα secretion." (PMID 29891920, 2018). "9-cis-retinoic acid is a metabolite of vitamin A and an agonist of PPARγ (via RXR ligation), and like rosiglitazone, has been shown to enhance CD36-mediated PE uptake and reduce malaria-induced TNF production in vitro." (PMID 21772838, 2012). "Here, we highlight recent advances in our current understanding of the biological actions of PPARγ on CD36 and malaria clearance from the hosts." (PMID 22287954, 2012). "In addition, recent advances in our current understanding of the biological actions of PPARγ on CD36 and malaria clearance from the hosts are highlighted." (PMID 22287954, 2012). "As a consequence, only Nrf2 but not PPARγ activators improve the outcome of severe malaria in vivo." (PMID 21949655, 2011).
malaria (continued). "During infection with Plasmodium berghei, malaria-susceptible mouse strains CBA and C57B6 had higher constitutive PPARγ levels compared to malaria-resistant BALB/c mice; however, in the susceptible mice, PPARγ did not translocate to the nucleus and the mice produced less plasmodicidal NO and H2O2." (PMID 30897154, 2019).
memory impairment (12 papers, 2018 to 2025). "Surprisingly, it has been reported that the PPARγ agonist (pioglitazone) improves tremor scores, motor disturbances, and spatial learning and memory impairments." (PMID 35591769, 2022). "Considering the roles of oxidative stress in age‐related learning and memory impairment, and considering the antioxidant role of PPARγ agonists, it was hypothesized that PPARγ activating by Pio may improve learning and memory in aging conditions." (PMID 36541251, 2022). "Could insulin and PPARγ agonists be used to ameliorate psychostimulant withdrawal-induced memory impairment?" (PMID 31396113, 2019). "Peroxisome proliferator-activated receptor gamma (PPARγ) agonists such as rosiglitazone and pioglitazone reduce amyloid and tau pathologies, inhibit neuroinflammation, and improve memory impairments in several rodent models and in humans with mild-to-moderate AD." (PMID 30420872, 2018). "For example, PPARγ agonists have been shown to decrease Aβ accumulation, either by reducing Aβ production or enhancing its clearance, thus counteracting neuroinflammation and improving memory impairments both in several AD rodent models and in humans with mild‐to‐moderate AD." (PMID 39510547, 2025). "Interestingly, in a PD rat model, the activation of the peroxisome proliferator-activated receptor gamma (PPAR-γ), which increases insulin sensitization and glucose metabolism, protected against MPTP-induced memory impairment." (PMID 38612620, 2024).
prostate tumor (12 papers, 2009 to 2024). "In particular, suppression of PPARγ in prostate tumor cells reduces proliferation, invasiveness, and anchorage-independent growth." (PMID 37894275, 2023). "Further analysis of prostate tumour lysates revealed that up-regulation of PPARG correlated with increased levels of its downstream metabolic effectors such as Fatty acid synthase (FASN), acetyl-CoA carboxylase (ACC) and ATP citrate lyase (ACLY)." (PMID 33654198, 2021). "It appears that the role of PPARG within the prostate tumour environment is critical for survival within the in vivo system due to the inherent pressures and stresses of the tumour environment." (PMID 33654198, 2021). "During the same time period clone OE19 was able to develop end-point tumours in all but one mouse, clearly indicating a requirement for PPARG for in vivo prostate tumour development." (PMID 33654198, 2021). "However, GSTP1 and PPARG were down-regulated in PTC but up-regulated in the profiled prostate tumor." (PMID 38790250, 2024). "Furthermore, PPARγ expression increases with tumor grade/stage, suggesting that PPARγ activity may play a pro-tumorigenic role in prostate tumors." (PMID 37894275, 2023). "Such a delayed disease onset might be attributed to the prostacyclin-dependent activity of the compounds, as prostacyclin was shown to inhibit lung tumor development in PPARγ-dependent mechanism that was also shown to be involved in tumor growth arrest in prostate tumors." (PMID 28270133, 2017). "PPARG gene is not expressed in normal prostate tissues but weakly expressed or not expressed in prostate tumor tissues." (PMID 35594510, 2022).
skin cancer (12 papers, 2008 to 2024). "Insufficient evidence was found for the associations between genetically proxied GLP1R, KCNJ11, ABCC8, and PPARG perturbations and skin cancer risk." (PMID 39640975, 2024). "Another epigenetic mechanism for the potential loss of PPARG expression in skin cancer is promoter hypermethylation." (PMID 39195246, 2024). "Yet, it should be noted that mice with heterozygous germline deletion of PPARγ or mice with epidermal-specific loss of PPARγ exhibit an increase in chemical carcinogen-induced skin tumors." (PMID 20508724, 2010). "The present findings support the utility of PPARγ activation by specific modulators, such as A02 and Octa, to prevent and treat keratinocyte-derived skin cancer." (PMID 37048080, 2023). "We investigated the possible role of the PPARγ activators Octa and the new compound (2Z,4E,6E)-2-methoxyocta-2,4,6-trienoic acid (A02) in targeting keratinocyte-derived skin cancer." (PMID 37048080, 2023). "Investigation of COX2 and PPARG protein expression in 323 benign and malignant skin tumors using a comprehensive multitumor TMA (TMA-1) was informative in 57.6% (186/323) and 65.6% (212/323) of cases." (PMID 19639032, 2009). "PPARγ knockout mice are characterized byan increased sensitivity to experimentally-induced skin tumors, emphasizing the tumor suppressorand differentiation promoting activity of PPARγ in the skin." (PMID 18596912, 2008). "In conclusion, targeting PPARγ may be useful for the prevention and treatment of keratinocyte-derived skin cancer." (PMID 37048080, 2023). "Results from these studies strongly support the hypothesis that targeting PPARγ may be useful for the prevention and treatment of keratinocyte-derived skin cancer." (PMID 37048080, 2023). "On the contrary, the activation of PPARγ did not prevent the development of UV- or DMBA/TPA-induced skin tumors, despite increased susceptibility of PPARγ+/− and keratinocyte-selective PPARγ-null mice to DMBA-mediated carcinogenesis." (PMID 19125181, 2008). "Thus, PPARγ agonists may represent a potential pharmacological target in the prevention or treatment of skin cancer." (PMID 37048080, 2023). "Whether PPARγ has a role in the prevention or treatment of skin cancer is under debate." (PMID 25655946, 2015). "Besides skin tumors, COX2 and PPARG expression was analyzed in many other benign and malignant tissue types from 46 different organs using a comprehensive multitumor TMA-1." (PMID 19639032, 2009).
autism (11 papers, 2007 to 2025). Persistent deficits in social interaction and communication and interaction as well as a markedly restricted repertoire of activity and interest as well as repetitive patterns of behavior. "Pioglitazone was able to control behavioral symptoms of autism, mainly due to the different effects of activated PPARγ, such as a reduction in the brain inflammatory response and an increase in mitochondrial function." (PMID 36834611, 2023). "Of particular interest to this case was the use of pioglitazone, a thiazolidinedione-class agonist of the peroxisome proliferator activated receptor gamma (PPAR gamma), in an autism population." (PMID 26491593, 2015). "Since L1-70’s interactions with TOP1, PPARγ and NDUFV2 contribute to the expression of two essential long autism genes and regulate important neuronal functions, we propose that L1 may not only ameliorate neurological problems, but also psychiatric dysfunctions." (PMID 36768419, 2023). "The current study provides evidence that treatment with the PPARγ agonist pioglitazone (Actos) does not induce any significant adverse effects, and may have a beneficial effect on patterns of aberrant social behavior in children with diagnosed autism." (PMID 17207275, 2007).